E2F8 (E2F transcription factor 8)
Diseases named in the same sentence as E2F8 in open-access papers (continued):
Sharing a sentence is not in itself a finding about the gene and the disease.
COVID-19 (2 papers, 2022 to 2025). A disease caused by infection with severe acute respiratory syndrome coronavirus 2. "SARS-CoV-2 also exploits the host cell cycle machinery to facilitate viral replication, suggesting that E2F7 and E2F8 may play a role in COVID-19 pathogenesis by modulating cell cycle and DNA repair pathways." (PMID 40408617, 2025). "Among the ten candidate hub genes, we found that 8 hub genes were differentially upregulated in HBV and COVID-19, so we further narrowed the scope of the study to 8 hub genes, including CDK1, E2F7, E2F8, TYMS, KIF20A, CENPE, TPX2, HMMR." (PMID 40408617, 2025). "GFI1, ZNF90, E2F8, E2F2, and EZH2 were also specific to exhausted T cells and may play a vital role in TEX in severe COVID-19." (PMID 35694714, 2022).
gallbladder cancer (2 papers, 2021 to 2025). "This study identifies the E2F8-RRM2 axis as pivotal mechanism underlying gemcitabine resistance in gallbladder cancer and demonstrates that targeting E2F8 significantly enhances tumor sensitivity to PARP inhibition." (PMID 41392282, 2025). "Quantification of IHC H-scores indicated that both E2F8 and RRM2 were significantly upregulated in recurrent compared with primary gallbladder cancers." (PMID 41392282, 2025).
injury (2 papers, 2020 to 2022). Damage inflicted on the body as the direct or indirect result of an external force, with or without disruption of structural continuity. "It is worth to further study whether E2f8 plays an important role in the development of HE and how the E2f8 in brain is regulated upon acute liver injury." (PMID 32174792, 2020).
lung adenocarcinoma (2 papers, 2018 to 2021). A carcinoma that arises from the lung and is characterized by the presence of malignant glandular epithelial cells. "In Hou’s dataset, E2F8 is overexpressed compared with that in the normal samples in all of the LC types: lung adenocarcinoma with a fold change of 3.659, large-cell lung carcinoma with a fold change of 4.707, and squamous cell lung carcinoma with a fold change of 2.48." (PMID 29754146, 2018). "The results indicated that the expression levels of E2F1, E2F2, E2F3, E2F5, E2F6, E2F7, and E2F8 were higher in lung adenocarcinoma and squamous cell lung carcinoma tissues than in lung tissues, whereas and the expression level of E2F4 was lower in the former than in the latter." (PMID 29754146, 2018). "In Su’s dataset, E2F8 is also overexpressed in lung adenocarcinoma with a fold change of 5.779." (PMID 29754146, 2018).
metastatic prostate carcinoma (2 papers, 2016 to 2020). A carcinoma that arises from the prostate gland and has spread to other anatomic sites. "E2F8 transcription factor is involved in cell angiogenesis and polyploidization, and epidemiological analysis has shown that E2F8 levels are elevated in metastatic prostate cancer, which is associated with poor prognosis." (PMID 32708169, 2020). "Epidemiological analysis showed that E2F8 is up‐regulated in metastatic prostate cancer and associated with poor prognosis." (PMID 27683099, 2016).
Obesity (2 papers, 2015 to 2020). Accumulation of substantial excess body fat. "Partial deficiency in the retinoblastoma protein gene, which is upstream of E2F8, protects against the development of obesity and associated metabolic disturbances, also consistent with our results." (PMID 26052340, 2015). "Moreover, it has been found that impaired glucose tolerance in obese individuals is associated with the up-regulation of E2F8, which possibly is implicated in the progression of obesity, glucose intolerance, and its complications." (PMID 32831068, 2020). "There is a limited number of studies related to E2F8 and obesity, however, these are still controversial." (PMID 26052340, 2015).
sarcoma (2 papers, 2020 to 2023). A usually aggressive malignant neoplasm of the soft tissue or bone. "However, not much is known about the role and clinical significance of E2F8 in leiomyosaroma, nor in other sarcomas." (PMID 37492373, 2023).
adenoma (1 paper, 2025). A neoplasm arising from the epithelium. "Time series analysis using the likelihood ratios showed differences in expression of genes including Fos, Lama3, Aldh1a3, Col7a1 and Doks associated with increased induction by t = 12 h, whereas E2f8, Exo1, Clspn, Kif14 and Kif12 all were decreased in Smad4+/+ adenomas." (PMID 40348815, 2025).
Allergy (1 paper, 2022). An allergy is an immune response or reaction to substances that are usually not harmful. "It should be pointed out that the roles of DBP and E2F8 in Th9 cells in the pathogenesis of other Th9-associated diseases such as allergy and asthma remain unknown and await further study." (PMID 36241625, 2022).
endometrial cancer (1 paper, 2020). Primary or metastatic malignant neoplasm involving the endometrium (mucous membrane that lines the endometrial cavity). "E2F8, E2F7, and E2F1 were the top three, most-frequently altered genes in endometrial cancer." (PMID 33329696, 2020).
fibrosarcoma (1 paper, 2022). A malignant mesenchymal fibroblastic neoplasm affecting the soft tissue and bone. "The same anti-tumoral and pro-tumoral effects of DBP and E2F8 on Th9 cells were verified in another experimental model of MCA205 fibrosarcoma." (PMID 36241625, 2022). "We also investigated whether IL-9 affects anti-tumor therapeutic effects in vivo in the MCA205 fibrosarcoma model and we found indeed that neutralization of IL-9 with anti-IL-9 antibody abolished the anti-tumor therapeutic effects of E2f8-knockdown Th9 cells." (PMID 36241625, 2022).
Giardia infection (1 paper, 2023). "Hence, we speculate that E2F1 may be regulated by E2F7 and E2F8 during Giardia infection, although the precise mechanism is still unknown." (PMID 37006313, 2023).
Hepatic steatosis (1 paper, 2015). Steatosis is a term used to denote lipid accumulation within hepatocytes. "Since activation of the PPARβ/δ complex inhibits hepatic steatosis, PPARβ KO-induced E2F8 suppression seems to worsen hepatic steatosis, which seems to be contrary to our result with MO-e2f8." (PMID 26052340, 2015). "Thus we hypothesized that E2F8 transcription factor mediated FABP3 transactivation might be a downstream of PPARα in the development of hepatic steatosis." (PMID 26052340, 2015).
keloid (1 paper, 2024). An irregularly shaped, elevated mark on the skin caused by deposits of excessive amounts of collagen during wound healing. "•CCNB1, EGFR, E2F8, BTG1, TP63, and IGF1 were associated with keloids." (PMID 39157347, 2024). "In comparison to levels in control tissues, the expression levels of CCNB1, EGFR, BTG1, as well as TP63 were evidently lower in the keloid tissues (P < 0.05), while the expression levels of E2F8 as well as IGF1 were evidently higher in the keloid tissues (P < 0.05)." (PMID 39157347, 2024). "A fibroblast-related diagnostic model for keloid based on a six-gene signature (CCNB1, EGFR, E2F8, BTG1, TP63, and IGF1) was proposed, showing high predictive accuracy in keloid diagnosis." (PMID 39157347, 2024). "The established model based on CCNB1, EGFR, E2F8, BTG1, TP63, and IGF1 showed good performance and may be useful for keloid diagnosis." (PMID 39157347, 2024). "In the training dataset, the expression levels of CCNB1, EGFR, E2F8, BTG1, as well as TP63 were remarkedly lower in the keloid samples than in the control samples (P < 0.05); however, the expression of IGF1 was evidently enhanced in the keloid samples elative to the control samples (P < 0.05)." (PMID 39157347, 2024).
leiomyosarcoma (1 paper, 2023). An uncommon, aggressive malignant smooth muscle neoplasm, usually occurring in post-menopausal women. "PORCUPINE highlighted genes and TFs that are enriched in driving heterogeneity among leiomyosarcoma patients, including RB1 and PPP2R1A as target genes, as well as the TFs E2F8 and ZNF282, which could potentially be inhibited." (PMID 37492373, 2023).
leukemia (1 paper, 2023). A malignant (clonal) hematologic disorder, involving hematopoietic stem cells and characterized by the presence of primitive or atypical myeloid or lymphoid cells in the bone marrow and the blood. "Specifically, TFs such as YY1, E2F1, and E2F8 were found to be closely associated with m6A activity within leukemia cells." (PMID 38022588, 2023).
medulloblastoma (1 paper, 2021). A malignant, invasive embryonal neoplasm arising from the cerebellum. "According to the Cavalli dataset, the high expression of E2F1, E2F2 and E2F8 correlates with poor prognostic outcomes in medulloblastoma patients." (PMID 35011618, 2021).
metastatic tumor (1 paper, 2016). "The averages of normalized E2F8 expression levels were calculated from benign, primary, and metastatic tumor samples; its relative expression levels were ‐0.054, −0.025, and 0.146, respectively (ANOVA test, P = 3.44e−12)." (PMID 27683099, 2016).
Miscarriage (1 paper, 2020). A pregnancy that ends at a stage in which the fetus is incapable of surviving on its own, defined as the spontaneous loss of a fetus before the 22th week of pregnancy. "Mapping of potential candidate genes at associated loci identified several genes (FGF9, TLE1, TLE4, E2F8, SIK1) with a plausible biological role in placental biology and miscarriage etiopathogenesis." (PMID 33239672, 2020).
myocardial infarction (1 paper, 2022). Gross necrosis of the myocardium, as a result of interruption of the blood supply to the area, as in coronary thrombosis. "The TF E2F8 regulates angiogenesis through activation of VEGFA in cooperation with HIF-1α19, while ABCG2 is associated with the cardiac repair of myocardial infarction and ECs survival." (PMID 35079076, 2022).
ovarian serous adenocarcinoma (1 paper, 2019). An adenocarcinoma that arises from the ovary and is characterized by the presence of malignant epithelial cells that, in well differentiated tumors, resemble the epithelium of the fallopian tube or, in poorly differentiated tumors, show anaplastic features and marked nuclear atypia. "A similar trend was found for E2F8 in Lu's and TCGA datasets: the mRNA levels of E2F8 in ovarian serous adenocarcinoma (fold change = 1.771 and p–value = 6.04E-05) and ovarian serous carcinoma (fold change = 3.136 and p–value = 7.97E-06) were significantly higher than those in the normal samples." (PMID 30967995, 2019).
pituitary tumor (1 paper, 2021). A benign or malignant neoplasm affecting the pituitary gland. "In contrast, loss of either E2f7 or E2f8 largely prevented the formation of pituitary tumors in Rb+/− mice." (PMID 33922435, 2021). "Surprisingly, additional deletion of E2f7 or E2f8 resulted in significantly lower pituitary tumor incidence compared to Rb+/− mice." (PMID 33922435, 2021). "This checkpoint-based hypothesis does not explain our observations that E2f7 or E2f8 deletion prevented pituitary tumor formation in the Rb+/− model." (PMID 33922435, 2021).
rectum cancer (1 paper, 2021). "The SNHG1 ceRNA network is common for all CRC sites, but only interacts with RFWD3 and E2F8 in the rectum, indicating a potential role for this network in rectum cancer." (PMID 34178670, 2021).
squamous cell carcinoma (1 paper, 2017). A carcinoma arising from squamous epithelial cells. "In addition, the effect of E2F8 overexpression on overall survival was similar in adenocarcinoma (P = 0.05) and squamous cell carcinoma (P = 0.08)." (PMID 29254182, 2017).
thyroid cancer (1 paper, 2020). "MiR-144 by targeting E2F8 could inhibit thyroid cancer progression via retarding G1/S transition." (PMID 33330110, 2020).
thyroid tumor (1 paper, 2021). A benign or malignant neoplasm affecting the thyroid gland. "The opposite trend occurred in Rb+/−8−/− mice, where loss of E2F8 reduced the incidence of Rb-deficient thyroid tumors." (PMID 33922435, 2021).
tumor (60 papers, 2014 to 2025). "Dysregulated expression of E2F8 has been implicated in tumor progression and therapeutic resistance across various cancers, highlighting its potential as a therapeutic target." (PMID 41392282, 2025). "Although E2F8 has been implicated in tumor progression and therapy resistance across various cancer types, specific inhibitors directly targeting this transcription factor remain unavailable." (PMID 41392282, 2025). "As expected, tumor cells with high E2F8 expression were associated with biological processes of DNA activity and were enriched in cell cycle and pathways related to DNA repair." (PMID 39021287, 2024). "Compared with the negative control, the knockdown of E2F2 resulted in the significant loss of tumor cell proliferation, while the knockdown of E2F8 increased tumor cell proliferation." (PMID 38371373, 2024). "Several studies have revealed that E2F8 acts as a transcriptional activator, positively increasing the expression of cyclin D1 (CCND1) in tumor cells, and a high expression level of E2F8 has been linked with poor prognosis." (PMID 36814821, 2023). "Several studies have shown that dysregulation of E2F8 is associated with oncogenesis and tumor progression in many cancers." (PMID 37492373, 2023). "In summary, our results indicated that the mRNA expression levels of E2F1, E2F3, E2F5, and E2F8 were significantly upregulated, and obvious and negatively associated with tumor stage for OC." (PMID 30967995, 2019). "We found that high E2F8 level was significantly associated with bigger tumor size(p = 0.0025), positive lymph node status(p = 0.0244) and advanced TNM stage(p = 0.0166)." (PMID 28270228, 2017). "Moreover, E2F8, tumor status and AJCC stage were identified as potential risk factors of DFS in HCC patients (all P < 0.1)." (PMID 31990034, 2020). "Although E2F8 expression was predominantly observed in the tumor epithelial cells, a weak stromal response was also detected." (PMID 41392282, 2025). "This is consistent with previous studies showing that E2F8 can maintain tumor cell proliferation and promote tumor cell migration." (PMID 40589640, 2025). "Among these features, five were clinical: pathological stage, new tumor event, number of lymph nodes, weight, age, and chemotherapy; and two were biological features: E2F8 and KCNQ1OT1." (PMID 41401030, 2025). "E2F8 has been shown to function as either an oncogene or tumor suppressor depending on cellular context." (PMID 38605607, 2024). "E2F8, a multifaceted transcription factor, exhibits both oncogenic and tumor suppressive activities in cancer, depending on the specific tumor type." (PMID 39456519, 2024). "Compared with the negative control, the overexpression of E2F2 accelerated tumor cell proliferation, while the overexpression of E2F8 inhibited tumor cell proliferation." (PMID 38371373, 2024). "To complete these observations, we stained and scored E2F1 and E2F8 protein expression in 154 tumor samples." (PMID 38686617, 2024). "E2F8 has also been shown to promote angiogenesis, which helps establish the tumor microenvironment and is positively correlated with tumor malignancies." (PMID 39057065, 2024). "The knockdown of E2F8 promoted proliferation and migration in tumor cells, validating E2F8 as a protective prognostic factor." (PMID 38371373, 2024). "E2F8 also plays an important role in the DNA damage response by preventing DNA synthesis when there is DNA damage, possibly resulting in less aggressive tumor growth and hence a better prognosis." (PMID 36575316, 2023). "High expression of E2F8 was related to tumor proliferation and a poor prognosis in a variety of tumors." (PMID 38149239, 2023). "We did not observe significant changes of mast cells and DCs in tumor tissues in Dbp- or E2f8-knockdowned Th9 cell treated tumor mice." (PMID 36241625, 2022). "Collectively, these data demonstrate that E2F8 plays a pivotal role in cell proliferation, tumor formation, and multiple oncogenic processes in GBM." (PMID 35409080, 2022).
tumor (continued). "Mononuclear phagocyte-based subclustering analysis also suggested low levels of E2F8 expression in peripheral tumours and adjacent normal tissues." (PMID 33499863, 2021). "Overall, these data demonstrate that E2F7 and E2F8 clearly contribute to the tumor formation in the pituitary glands of Rb+/− mice, while in the thyroid glands, loss of atypical E2Fs does not have a significant impact on RB loss dependent tumorigenesis." (PMID 33922435, 2021). "For other genes, AURKA, PTTG1, CDC20, SLC7A5, E2F8, TPX2, and TUBA4A, high expression in the high-risk group was linked to tumour growth and metastasis." (PMID 34131308, 2021). "E2F8 high expression is strongly associated with a worse outcome of GBM patients and radio-resistance while E2F8 knockdown decreased proliferation and tumor growth and inhibited invasion, migration and the expression of genes implicated in metastasis." (PMID 33804958, 2021). "Temporal-specific ablation strategies recovered that E2F8 exerts tumor suppressor effects in postnatal liver development during the first 2 weeks of life." (PMID 31990034, 2020). "The E2F8 expression was remarkably positively related to tumor purity (r = 0.335, P = 2.00e − 12) in GBM." (PMID 33381564, 2020). "Analysis demonstrated that the expression of E2F8 was significantly associated with gender, carcinoembryonic antigen (CEA) level, tumor differentiation, pathological type, vascular invasion, neural invasion, and distant metastasis." (PMID 33224876, 2020). "After adjusting tumor status, AJCC stage and new tumor event after initial treatment in multivariate Cox regression model, high level of E2F8 showed to be an independent risk factor for OS in HCC patients (HR = 2.16, 95%CI = 1.3–3.59, P = 0.003)." (PMID 31990034, 2020). "In terms of DFS, patients with increased E2F1 (p < 0.001), E2F2 (p < 0.001), E2F7 (p < 0.001), and E2F8 (p = 0.001) tumor expression have a poorer prognosis." (PMID 33061852, 2020). "After adjusting tumor status and AJCC stage in multivariate Cox regression model, high level of E2F8 showed to be an independent risk factor for DFS in HCC patients (HR = 1.64, 95%CI = 1.19–2.25, P = 0.002)." (PMID 31990034, 2020). "Univariate analysis showed that E2F8, tumor status, AJCC stage and new tumor event after initial treatment were potential risk factors of OS in HCC patients (all P < 0.1)." (PMID 31990034, 2020). "We confirmed the function of E2F8 in vivo, signifying that E2F8 knockdown was significantly correlated with reduced tumor size and weight." (PMID 32823614, 2020). "Variables including E2F8, gender, body mass index, race, tumor status, family history of cancer, pathological grade, AJCC stage, vascular invasion, AFP, new tumor event after initial treatment and hepatic inflammation were included in the univariate analysis." (PMID 31990034, 2020). "E2F8 overexpression in HCC facilitated the tumor occurrence and aggressiveness through activating a E2F1/Cyclin D1 signaling pathway to regulate the G1-S transition or transcriptionally suppressing CDK1 to induce hepatocyte polyploidization." (PMID 31990034, 2020). "E2F7 and E2F8 act as tumor suppressors via transcriptional repression of genes involved in S‐phase entry and progression." (PMID 31475738, 2019). "In this study, E2F8 was significantly overexpressed in OC tissues, and its expression was markedly and negatively correlated with the tumor stage of patients with OC." (PMID 30967995, 2019). "In the present study, E2F7 and E2F8 were significantly overexpressed in LC tissues, and their expression levels were markedly correlated with the tumor stage of the patients with LC." (PMID 29754146, 2018). "We also identified miR-144 as a tumor-suppressive microRNA that directly targeted E2F8 to inhibit proliferation of PTC cells in vitro and in vivo." (PMID 28270228, 2017). "To assess the oncogenic role of E2F8 in vivo, we established xenograft tumor models using TPC-1 cells transfected with shRNA-NC and shRNA-E2F8." (PMID 28270228, 2017).